RNU6-1271P (RNA, U6 small nuclear 1271, pseudogene)
Gene: Small nuclear RNA gene on chromosome 12 (76,139,567 to 76,139,671, forward strand). Ensembl gene ENSG00000252858.
Homologues: Orthologues: chimpanzee U6 (99% identical), rabbit U6 (79% identical), guinea pig U6 (77% identical). Paralogues in human: RNU6-20P (87% identical), RNU6-211P (87% identical), RNU6-434P (87% identical), RNU6-1316P (86% identical), RNU6-21P (86% identical), RNU6-1152P (85% identical), RNU6-144P (85% identical), RNU6-214P (85% identical), RNU6-280P (85% identical), RNU6-35P (85% identical), RNU6-463P (85% identical), RNU6-641P (85% identical), and 1285 more.